RNU6-791P (RNA, U6 small nuclear 791, pseudogene)
Gene: Small nuclear RNA gene on chromosome 1 (222,503,632 to 222,503,735, reverse strand). Ensembl gene ENSG00000222399.
Homologues: Orthologues: macaque U6 (91% identical), pig U6 (84% identical), pig U6 (78% identical), dog U6 (77% identical). Paralogues in human: RNU6-1076P (100% identical), RNU6-1100P (100% identical), RNU6-1118P (100% identical), RNU6-1217P (100% identical), RNU6-355P (100% identical), RNU6-447P (100% identical), RNU6-785P (100% identical), RNU6-860P (100% identical), U6 (100% identical), RNU6-1054P (99% identical), RNU6-1199P (99% identical), RNU6-1319P (99% identical), and 1289 more.